CD44 (CD44 molecule (IN blood group))
Diseases named in the same sentence as CD44 in open-access papers (continued):
Sharing a sentence is not in itself a finding about the gene and the disease.
cancer (continued). "Next, we explored the functional role of CD44 in TME of various cancer types using CancerSEA database, which shows the correlation of CD44 with malignant phenotype and functional states at single-cell resolutions." (PMID 37117249, 2023). "The standard isoform of CD44 (CD44s) is ubiquitously expressed in all vertebrates, whereas CD44v is mainly expressed during inflammation and cancer." (PMID 37568628, 2023). "The relative gene expression of the stem cell markers OCT4, SOX2, and NANOG was evaluated to confirm the cancer stem cell features of the CD44+ cells." (PMID 36902135, 2023). "CD44–HA interactions promote cell proliferation, migration, and invasion in inflammation and cancer progression." (PMID 37762403, 2023). "These include cancer stem cell (CSC) markers: (i) surface receptors, including EpCAM/CD326, CD44 variants, Notch-ligand Dll4, prominin/CD133, (ii) extracellular ligands, including Wnt, and (iii) functional enzymes (ALDH and MMPs)." (PMID 36671802, 2023). "Several cancer stem cell markers, CD44, CD133, and Oct3/4, were positive, and ALP was partially positive." (PMID 37949965, 2023). "We previously found that CD44 high expressing cancer cells were distributed to the front edge during collective migration of luminal type BrCa." (PMID 37842093, 2023). "EBV infection significantly upregulated the expression levels of cancer stem cell (CSC) markers such as CD44 and CD133 in the xenograft model." (PMID 37762374, 2023). "Another evidence-synthesis study based on 5788 cancer patients indicated that CD44 polymorphism rs13347 acts as a risk factor for cancer, especially in Chinese people, while the minor allele of polymorphism rs11821102 may be associated with a decreased susceptibility to cancer." (PMID 37958796, 2023). "Many studies reported CD44 as a biomarker of cancer stem cells (CSCs) and promoter of epithelial-mesenchymal transition." (PMID 37886001, 2023). "Strikingly, despite cumulative missing values across 170 single cells, we identify CD44, a cell surface adhesion receptor expressed in many cancers and involved in metastasis, as differentially expressed." (PMID 37839701, 2023). "For instance, the activated STAT3 enriches the expression of CD44, physically interacts with CD44 and NF-κB, activates the telomerase (hTERT), promotes a cancer stem phenotype." (PMID 37642779, 2023). "Given the significant involvement of CD44 in cancer cell growth, researchers have extensively studied its expression profile across various types of cancers." (PMID 37491225, 2023). "Similar to integrin, other receptors such as DDRs, CD44 and syndecans are potential target for anti-cancer therapy." (PMID 36906534, 2023). "Curcumin conjugated as an ester to cholesteryl–hyaluronic acid nanohydrogels can target delivery to drug-resistant cancer cells expressing CD44." (PMID 38139827, 2023). "Taken together, these data show that CD44 is instrumental in the acquisition and maintenance of cancer hallmarks by sustaining proliferative signalling and evading apoptosis." (PMID 37958796, 2023). "Conversely, a ligand for the cancer stem cell receptor CD44 led to reductions in BMF, BIM, and apoptosis." (PMID 37761989, 2023). "CD44 is a transmembrane cell surface glycoprotein and a marker for cancer stem cells in many solid tumors." (PMID 38067149, 2023). "We identified the ankyrin-binding domain of CD44 ICD as the primary site of CD44–iASPP interaction, which differed between normal and cancer cells." (PMID 37894408, 2023). "The hazard ratio for the death of patients with CD44-positive cancer was 6.8 (95% CI 2.4–19.2, p ≤ 0.001), and carboplatin-resistant or carboplatin-refractory disease was an independent predictor of mortality." (PMID 38201468, 2023). "As previously reported, the CD24 and CD44 cell surface proteins have been recognized as CSC markers in other cancers." (PMID 36737794, 2023).
cancer (continued). "In extracted CD44+/ALDH1+ cells from HNSCC that exhibited cancer stem cell features (CSC), they also discovered the dysregulation of this miRNA." (PMID 37205904, 2023). "CD44 isoforms are present in actively dividing cells during embryonic development and can also be found in specific cancer types under certain circumstances, particularly in advanced stages." (PMID 37491225, 2023). "This approach helped distinguish between CD271-positive cancer cells and lymphocytes that also express this protein, and allowed for the detection of CD44/CD271 double-positive cells that likely represent CSCs." (PMID 38003753, 2023). "The CD44 protein is engaged in many cellular functions critical to cancer progression and metastasis, including migration and cell–cell and cell–matrix adhesion." (PMID 36831550, 2023). "First, HA acts as a targeting moiety, allowing the drug to selectively bind to and enter cancer cells that have an elevated CD44 expression." (PMID 37958796, 2023). "The cell cultures were evaluated for the presence of cancer stem cell markers (CD44, CD133, CD15, and CD171) and cell proliferation rate." (PMID 37998351, 2023). "In another work, biodegradable NPs which can target tumors were developed for photothermal therapy (PTT) against human cancer cells that overexpress CD44." (PMID 37376161, 2023). "HA’s potential also was revealed for cancer treatment thanks to its interaction with the CD44 R. This receptor plays a crucial role in the invasion and metastatic processes of several human cancers." (PMID 37373443, 2023). "We also analyzed the expression of cancer stem cell markers ALDH1A1, CD24, and CD44, which are often associated with EMT induction." (PMID 37834189, 2023). "Studies have demonstrated that CD44-positive cancer cells in gastric cancer exhibit resistance to chemotherapy and radiation therapy." (PMID 37491225, 2023). "In their work, the authors analyzed the presence of other cancer stem cell markers, including CD44+/CD24+/EPCAM+ and CD133+." (PMID 37371030, 2023). "Although CD44 is usually overexpressed in cancer cells, HA, known as CD44 receptor-mediated targeting, is a good choice of polymer to carry the anticancer drug more efficiently." (PMID 36826291, 2023). "In the cancer field, previous studies have also demonstrated that surface nano-patterns and interfacial geometry enhance CD44+/CD24- ESA+ and other stem markers, highlighting the relevance of surface topographies to enrich CSC populations for isolation." (PMID 36968199, 2023). "CAF-D (CD44+ CD90+ α-SMAhigh/BMP4 low) synthesized TGF-β1 that are essential for cancer invasion, whereas CAF-N (CD44+ CD90+ α-SMAlow/BMP4 high) included intrinsically motile fibroblasts." (PMID 37024932, 2023). "In vitro experiments show that the designed hybrids can selectively deliver to CD44-overexpressing cancer cells, inhibit cancer cell proliferation, and enhance CT imaging." (PMID 37376161, 2023). "Overall, HA-modified delivery systems leverage CD44 overexpression in cancers to achieve active targeting of chemotherapeutics specifically to non-CSC and CSC populations." (PMID 38102651, 2023). "Since this molecule plays an essential role in different activities of cancer cells new hopes raised for immunotherapy to target CD44-expressing malignant cells." (PMID 36759786, 2023). "Second, it plays a role in the evasion of apoptosis, as CD44 overexpression can activate anti-apoptotic pathways, allowing cancer cells to survive chemotherapy-induced cell death." (PMID 37958796, 2023). "Milk exosomes, the surface of which was modified with hyaluronic acid and loaded with doxorubicin, selectively delivered doxorubicin to cancer cells over-expressing CD44 and exhibited increased antitumor activity." (PMID 37373342, 2023). "ALDH+ CD44+ cancer cells are considered CSCs in HNSCC and exhibit increased tumorigenicity through the aberrant activation of the PI3K/mTOR signaling pathway and upregulation of SOX2 expression." (PMID 37711747, 2023).
cancer (continued). "The isoform CD44v of the cancer stem cell marker CD44 mediates the reactive oxygen species (ROS) defense through stabilizing xCT (a cystine–glutamate transporter) and inducing glutathione synthesis." (PMID 38247453, 2023). "CD44 proteins are primary HA receptors that promote invasion and metastasis of cancer cells by modulating intracellular signaling through its interaction with RHAMM." (PMID 36936902, 2023). "MMP9 has the ability to degrade the ECM components and plays a crucial role in cancer invasion, and it is frequently co-expressed with CD44 in ccRCC." (PMID 37509716, 2023). "Accumulating evidence indicates that isoforms of the multifunctional cell-surface glycoprotein CD44 play different roles in cancer cells as compared to normal cells." (PMID 38106992, 2023). "Whereas CD11b is mainly regulated by calcium-controlled receptor recycling, it has been shown in cancer cells that the extracellular domain of CD44 is also cleaved in a calcium-dependent manner." (PMID 37729408, 2023). "Designing a vaccine to elicit both cellular and humoral immune responses seems difficult, although it has been observed through anti-CD44 vaccination in some cancer patients." (PMID 36759786, 2023). "Due to the functional importance of laminin γ2, TSG6, and CD44 in cancer migration and invasion as components of ECM, understanding their regulatory mechanism is important in the development of therapeutic strategies." (PMID 36793862, 2023). "Studies have suggested that CD44 plays important roles in malignant progression of tumors through its cancer stemness and metastasis-promoting properties." (PMID 37218897, 2023). "Hyaluronic acid (HA), a natural anionic polysaccharide, possesses a high affinity to cancer overexpressed biomarkers (e.g., CD44 or RHAMM) and is widely used as a targeting moiety for drug and PDT agent delivery carrier functionalizations." (PMID 37765191, 2023). "Hyaluronic acid (HA)-based nanogels are unique drug delivery vehicles that combine the intrinsic targetability of HA to CD44-overexpressing cancer cells with the stimulus-responsive behavior of the nanogels." (PMID 38140012, 2023). "A clear association of CD44, PTGER4, and α4β1 in SN macrophages, plasma cells, cancer cells, and T cells was observed with upregulated SPP1 in macrophages." (PMID 37745301, 2023). "Quite unexpectedly, we also identified Cluster 4 to be enriched for small population of both EpCAMhigh and EpCAMlow cells with CD90/CD44/Vimentin/Ki‐67high molecular profile, resembling proliferative cancer stem‐like (CSC) subpopulation." (PMID 36550781, 2023). "Here we show that the cell surface glycoprotein CD44, which marks the acquisition of distinct cell phenotypes in the context of development, immunity and cancer progression, mediates the uptake of metals including copper." (PMID 37100912, 2023). "The treatment increase the amount of the CD44+/CD133+ populations suggesting an increase in the quantity of cancer stem cells." (PMID 36968194, 2023). "This was in agreement with the current view that CD44 plays an indispensable role in activating survival pathways that protect cancer cells from apoptosis, as described in the following paragraph." (PMID 37958796, 2023). "Extensive literature reports have highlighted an upregulation of CD44 mRNA expression across multiple cancer types, particularly on cells displaying EMT phenotype." (PMID 38455361, 2023). "Based on their research, CD44 has a connection with both cancer progression inhibition and promotion." (PMID 38188613, 2023). "Several peptide migration inhibitors have been explored in cancer drug development because cell–cell and cell–matrix proteins, such as CD44, different integrins, and cell surface proteins are recognized as interesting anticancer drug targets." (PMID 36921670, 2023). "More specifically, we have shown that CS-E is a potential ligand for designing nanoprobes to target CD44-overexpressed cancer cells and neurites." (PMID 36325647, 2023).
cancer (continued). "Cancer stem cells have been characterized by certain specific markers, including CD44, CD90, CD133, CD271, aldehyde dehydrogenase 1 (ALDH1), and epithelial cell adhesion molecule." (PMID 38328436, 2023). "Since CD44 is a key receptor for HA, it has been targeted in different therapeutic strategies against cancer, such as vaccines, anti-CD44 antibodies, and nanoparticles that deliver CD44 siRNA." (PMID 36936902, 2023). "HA is the major ligand for CD44, which is a multifunctional mediator of cancer progression involved in promoting proliferation, motility, invasiveness, angiogenesis, and chemoresistance." (PMID 37110670, 2023). "Using the appropriate antibodies and the flow cytometry method, cancer stem cells with the CD44(+) CD24(+) phenotype were identified in each material." (PMID 38201547, 2023). "The growing and seemingly promising use of splicing inhibitors for treating cancer and other pathologies gives hope for the prospect of using such an approach to regulate CD44 alternative splicing." (PMID 38106992, 2023). "CD44 is essential for the adaptation of disseminated cancer cells to new environments and facilitates metastatic colonization." (PMID 37491225, 2023). "The study concludes that CD44 can be a potential diagnostic and prognostic biomarker for HNSCC and offer new molecular targets for CD44-targeted therapy for cancer management." (PMID 37593530, 2023). "The hyaluronan functionalized mExo-Dox has shown selective doxorubicin delivery to CD44 overexpressing cancer cells and promoting more significant cell death." (PMID 37190185, 2023). "CD44+/CD24−/low BCSC play a crucial role in cancer invasion, as cell lines with a higher proportion of CD44+/CD24−/low cells exhibit greater expression of pro-invasive genes, such as interleukin-1 alpha (IL1α), interleukin-6 (IL6), and interleukin-8 (IL8)." (PMID 37445860, 2023). "Prospective studies will help confirm the role of CD44, as a marker of both poor prognosis and poorer response to anti-cancer treatments." (PMID 36831554, 2023). "HA-binding CD44 activates numerous signaling pathways that participate in various cellular events of cancers, including migration, invasion, proliferation, survival, stemness, drug resistance, and many other functions involved in malignant properties." (PMID 37835592, 2023). "All of these necessitate further research into the role of RBPs mentioned in the review in each type of cancer and the identification of other possible regulators of CD44 alternative splicing." (PMID 38106992, 2023). "For instance, CD44 is overexpressed in many cancer types, including breast and colorectal cancer, and this overexpression is most prominent in the cancer stem-like cells within individual tumors being strongly associated with drug resistance and metastases." (PMID 37189846, 2023). "As previously reported, CD44 is overexpressed in CSCs and plays a vital role in cancer progression, metastasis, and drug resistance." (PMID 37117249, 2023). "Primary culture of the malignant tumors of the converted cells exhibited the elevated expression of CSC related genes CD44, CD24 and EPCAM maintaining the expression of stemness genes." (PMID 37181678, 2023). "The expression of CD44-ICD is specific to cancer stem cells, and the hypoxic environment greatly affects CD44-ICD pathways." (PMID 37835592, 2023). "Although CD44 has been extensively studied in context of cancer migration, few researches have been carried out to explore its role in regulating lamellipodia outgrowth in cancer migration." (PMID 37842093, 2023). "IF double staining revealed the presence of CD44/CD271 double-positive cells notably within the tumors’ invasive fronts that likely correspond to cancer stem cells." (PMID 38003753, 2023). "Qin and coworkers developed an HA-modified pH-responsive nanocarrier via the electrostatic adsorption of HA on the positively charged HB-polymer nanoparticle surface and used it for targeted delivery to CD44-overexpressed cancer cells." (PMID 37765191, 2023).
cancer (continued). "In CRC, markers such as CD133, CD44, Oct-4, and Nanog are commonly used to identify and isolate cancer stem cells." (PMID 37762705, 2023). "CD44 is a receptor for hyaluronic acid, collagen, fibronectin and growth factors, and thus regulates signaling pathways related to cancer proliferation, invasion, metastasis, and treatment resistance." (PMID 37711747, 2023). "CD44 is a transducer of cancer-specific signals from the cellular environment and a known cancer stemness and metastasis regulator." (PMID 36834653, 2023). "OPN has been widely implicated in cancer invasion and metastasis, poor prognosis and resistance to radiation and chemotherapy through promoting cancer stem cell-like properties and binding with CD44 or integrin receptors." (PMID 37032358, 2023). "The authors used the CD44-HA interaction to target the cancer cells and thiolated-hyaluronic acid labeled with Nile blue was used to stabilize the nanoprobes." (PMID 37754116, 2023). "CD44 is suggested to be a surface marker for cancer stem-like cells (CSCs), which are resistant to ROS-induced damage and have low levels of intracellular ROS." (PMID 37107200, 2023). "The binding ability of HA to CD44 allows it to internalize into cells, which makes it a promising candidate to suppress the progression of cancers." (PMID 37376161, 2023). "This study still has some limitations, biological validation and large sample cancer cohort validation should be performed to better illustrate the role of CD44 in the pan-cancer study." (PMID 37117249, 2023). "Although TIMP1 is a natural inhibitor of MMPs involved in the matrix remodeling during carcinogenesis, it converges toward cancer cell survival by binding MMP9/CD44 complex and mediating PI3K/AKT pathway activation." (PMID 36906579, 2023). "Unexpectedly, the immune score and stromal score were positively correlated with CD44 expression in every cancer type in both groups." (PMID 37117249, 2023). "Cancer cells highly express a large number of unique receptors on their surface, such as transferrin receptor 1 (TfR1) and CD44." (PMID 36678599, 2023). "In the following paragraphs, I will explore the CD44-dependent molecular mechanisms regulating key cellular functions that are thought to be important in cancer pathophysiology." (PMID 37958796, 2023). "The present study systematically assessed the predictive significance of CD44 expression in 33 cancer types using The Cancer Genome Atlas (TCGA) database." (PMID 37117249, 2023). "CD44 functions as a major adhesion molecule and in the cellular internalization of hyaluronic acid in both normal and cancer cells." (PMID 37173926, 2023). "Extensive studies revealed that high CD44 expression correlates with a mesenchymal phenotype of cancer stem cells and participates in the EMT, resulting in tumors with worse prognosis showing highly invasive, metastatic, and chemo-radiation-resistant features." (PMID 37835592, 2023). "The binding affinity of HA to CD44 molecules expressed on cancer cells has made HA a promising tool in cancer therapy, and it has been widely used for this purpose." (PMID 37376161, 2023). "CD44 is vital in integrating cellular microenvironment cues with generating various gene expressions such as cell survival, which is crucial in vaccine cancer platforms." (PMID 36975676, 2023). "Sarli and collaborators evaluated the intramammary/intratumoral and extramammary/extratumoral expression of CD44 in feline normal mammary tissues, benign tumors, and malignant tumors in relationship to lymphangiogenesis." (PMID 36899736, 2023). "Consistently, the biomarkers of cancer stem cells - CD44 and EpCAM - were both downregulated in circRABL2B overexpressed cells." (PMID 37324942, 2023).